NDC80 (NDC80 kinetochore complex component)
Diseases named in the same sentence as NDC80 in open-access papers (continued):
Sharing a sentence is not in itself a finding about the gene and the disease.
tumor (continued). "Together, our results indicated that these genes having higher association with NDC80 complex components in tumor tissues compared to normal tissues were functional partners associated with the oncogenic roles involved in cell growth of NDC80 complex components in the tumor context." (PMID 39513104, 2024). "Our results suggested upregulated NDC80 complex components in the tumor context may promote tumor cancer progression and influence patient survival by interacting with Th2 cell infiltration." (PMID 39513104, 2024). "Depletion or inhibition of NDC80 induced mitotic arrest, and suppressed xenograft tumor growth." (PMID 34207779, 2021). "Seven pairs of tumor and adjacent non-tumorous tissues were selected to verify the expressions of the ZWINT, RRM2, NDC80, KIF4A, CEP55, CENPU, and CENPF genes." (PMID 35028418, 2022). "As part of the ISG family, overexpression of NDC80, NPAS2, and AHNAK2 changed tumor microenvironment." (PMID 35813478, 2022). "In this study, it was found that NDC80, NUF2, SPC24 and SPC25 genes were differentially expressed in tumor tissues and normal tissues and NDC80, NUF2, SPC24 and SPC25genes have diagnostic values for LUAD." (PMID 32226507, 2020). "The NEK2, NDC80 and CEP250 mRNA expressions were different in relation to age, weight, recurrence status, histological grade, family HCC history, pathologic stage, tumor size, and survival time." (PMID 33109182, 2020). "NDC80 and SPC25 expression, TNM grade, tumor status, residual tumors, radiotherapy were used to construct a nomogram for risk assessment." (PMID 32226507, 2020). "Of these hub genes, only four genes, CDK1, NDC80, KIF11, and COL4A2, were shared between the two groups, whereas 189 hub genes from the normal group replaced 101 different hub genes from the tumor group, resulting in protein–protein network differences between the normal and tumor groups." (PMID 40457491, 2025). "Heretofore, none of studies has focused on how the up-regulated NDC80 in tumor tissue specifically affected the activation and biological properties of immune cells." (PMID 35813478, 2022). "The NDC80 complex, including the main elements of NDC80, SPC24, and SPC25, is highly expressed in various tumors and cooperatively promotes the invasion and metastasis of tumor cells." (PMID 33778011, 2021). "The fusion protein retains the kinetochore microtubule binding region of NDC80, suggesting possible mislocalization that was, however, not experimentally addressed; within the tumor samples, FGFR2-NDC80 localized predominantly to the cell membrane." (PMID 34207779, 2021). "The combined detection of NDC80, NUF2, SPC24 and SPC25 may become a new research direction in tumor diagnosis and a new target for tumor targeted gene therapy." (PMID 32226507, 2020). "The combined detection of NDC80, NUF2, SPC24 and SPC25 may become a new research direction in LUAD diagnosis and a new target for tumor targeted gene therapy." (PMID 32226507, 2020).
infection (2 papers, 2020 to 2023). The state of being infected such as from the introduction of a foreign agent such as serum, vaccine, antigenic substance or organism. "During oocyst development and sporozoite formation, live cell imaging revealed NDC80–GFP fluorescence at multiple foci adjacent to the nuclear DNA at various stages of oocyst development from 7 days post-infection (d.p.i.)of the mosquito to 21 d.p.i., as well as a single focus in mature sporozoites." (PMID 32501284, 2020).
NDC80 also shares sentences with these, for which no sentence is quoted: gastric cancer (7 papers); adenocarcinoma (2); female infertility (2); Infertility (2); lymph node metastasis (2); non-small cell lung carcinoma (2); abortion (1); autoimmune (1); brain tumors (1); cervix adenocarcinoma (1); colon adenocarcinoma (1); colorectal adenocarcinoma (1); dysplasia (1); endometrial cancer (1); intrahepatic cholangiocarcinoma (1); leiomyoma (1); liver cirrhosis (1); mesothelioma (1); metastasis (1); myeloma (1); neuroblastoma (1); pancreatic adenocarcinoma (1); prostate adenocarcinoma (1); stomach cancer (1); testicular germ cell tumor (1); trigonocephaly (1); type 1 diabetes (1); uveal melanoma (1); virus infection (1).